CCR1 (C-C motif chemokine receptor 1)
Diseases named in the same sentence as CCR1 in open-access papers (continued):
Sharing a sentence is not in itself a finding about the gene and the disease.
infection (continued). "Histological findings of immune cell infiltration in tracheal tissues after infection with swH1N1 was in line with induction of cytokines and chemotactic factors (AMCF-II, CXCL8/IL8, CXCL2, CXCL10, and CCL20) as well as receptors (CCR1 and CXCR2) in lower trachea after this infection." (PMID 39247193, 2024). "The positive correlation with CXCL1, CXCL16, and CCR1 indicated that PGK1 may contribute to the recruitment of immune cells, such as macrophages and T cells, to the site of infection or inflammation." (PMID 39712033, 2024). "Upon infection, we found that rs71327024 continued to be a significant emVar, with the introgressed allele driving 1.12 times more expression of GFP from the CCR1 promoter than the non-introgressed allele." (PMID 36763080, 2023). "In the early stage of infection by Foc1, PAL, C4H, 4CL, CCR1, and COMT were up-regulated, and only one 4CL and one CCR1 were down-regulated, whereas CCoAOMT was up-regulated, and one F5H was down-regulated after Foc4 infection." (PMID 33176672, 2020). "Overall, these results suggest that ITC are prepared to buffer ROS at baseline, a useful adaptation for effector cells expressing chemokine receptors, such as CCR1, CCR2, and CCR5 that direct them to the same sites of infection or inflammation as monocytes and neutrophils." (PMID 30737409, 2019). "MIP-1α signals through CCR1, CCR4, and CCR5 and MIP-1β signals directly through the CCR5, suggesting that pregnancy may induce different pathways signaling in response to infection." (PMID 29176767, 2017). "CCL5, CCR1, CCR3 and CCR5 mRNA expression was also detected in brains of Swiss Webster mice and appeared to contribute to the inflammatory response that results in cellular degradation in the cerebellum during Plasmodium yoelii (17XL) infection." (PMID 24476686, 2014). "Infection with both low and high virulence isolates resulted in down-regulation of mRNA levels for chemokines CCL2, CCL3L, CXCL2 and chemokine receptors CCR1, CCR5, CXCR3, CXCR4 and up-regulation in expression of mRNAs for CCL4, CXCL10 and chemokine receptor CCR7." (PMID 23265239, 2013). "The observed down-regulation of chemokine (CCL4) and chemokine receptors (CCR1, CXCR2, CX3CR1, C5aR) could impair the proper inflammatory response at the site of infection as they play a crucial role in immune cell trafficking." (PMID 23626859, 2013). "Also contrasting with the results described here from the studies of in vivo infections, levels of mRNA for CCL3, CXCL2, CCR1 and CCR5 were down-regulated compared to mock-infected cells following infection in vitro." (PMID 24083897, 2013). "To assess quantitatively and temporally the effect of Ccr1 on specific leukocyte accumulation in the model, we harvested leukocytes from the organs and defined their immunophenotypes by FACS on days 3, 6, 9 and 12 post-infection." (PMID 22916017, 2012). "Strikingly, the effect of Ccr1 on neutrophil accumulation in the kidney was not seen until the late phase of the infection, when the receptor was up-regulated on the neutrophil surface." (PMID 22916017, 2012). "We have not investigated here the role of CCR5 to infection outcome but it is clear that CCR1–/– mice had no major phenotype when infected with an inoculum which causes severe disease in mice." (PMID 21206747, 2010). "The results of this study demonstrate that the increase in production of RANTES follows the course of P. yoelii 17XL malaria infection, thus RANTES and its receptors CCR1, CCR3 and CCR5 were detected at their highest levels at day six and day eight post-infection." (PMID 16359553, 2005). "Expression of MIP-1α and MIP-1β could recruit NK cells, which express CCR5, and immature dendritic cells, which express CCR1 and CCR5, into the site of infection." (PMID 15507126, 2004).
infection (continued). "Additionally, blockade of CCR1 and CCR5 in models of Herpes Simplex Virus Type 2 infection impaired host defense and altered the cytokine response, indicating a protective role for these receptors during infection." (PMID 40859641, 2025). "Likewise, mature plants lacking hm1 function are completely susceptible, demonstrating that HCTR is absolutely required for CCR1 infection, and mature maize plants are not protected from toxin-mediated disease spread." (PMID 30332488, 2018). "The lack of IFNγ expression within the brain and absence of CCR1 on microglia may prevent their activation, thus contributing to the shift in viral tropism to resident microglia which consequently became the main target of infection." (PMID 37037810, 2023).
neurological diseases (4 papers, 2020 to 2023). "The activation of CCR1 is pro-inflammatory in neurological diseases, and it is expressed in various cell types in the brain, including smooth muscle cells, astrocytes, and neurons." (PMID 37108638, 2023). "C-C chemokine receptor type 1 (CCR1) activation is pro-inflammatory in several neurological disorders." (PMID 37108638, 2023).
cardiovascular disease (2 papers, 2018 to 2024). "Of all chemokines, the CC-chemokine receptors CCR1 and CCR5 and their ligand CCL5 appear to play a particular role in cardiovascular diseases." (PMID 30006564, 2018).
immune diseases (2 papers, 2024). "Given that CCL3-CCR1 participates in inflammation, various antagonists or inhibitors of CCR1 are developed to cure diseases associated with immune disorders." (PMID 38475811, 2024).
nephropathy (2 papers, 2005 to 2022). A nonspecific term referring to disease or damage of the kidneys. "The therapeutic impact of the blockade of CCR1, CCR2, CCR4, CCR5, or the corresponding ligands has been further studied in various renal disease models." (PMID 16200331, 2005).
adenocarcinoma (1 paper, 2015). A common cancer characterized by the presence of malignant glandular cells. "Based on our present study, we hypothesise that human lung AAH lesions, the precursors for adenocarcinomas, may respond to chemopreventive interventions targeting the microenvironment with CCR1 inhibitors, NPC2 protein itself or chemicals that up-regulate NPC2 expression." (PMID 26183450, 2015).
animal disease (1 paper, 2022). "For instance, CCR1, CCR7, or CXCR4 modification was found to enhance the migration of MSCs to the injured myocardium, secondary lymphoid organs, and infarcted myocardium, respectively, and to promote recovery in animal disease models." (PMID 35123561, 2022).
inflammation (1 paper, 2025). Aberrant reaction of the microcirculation characterized by movement of fluid and leukocytes from the blood into extravascular tissues. "Eosinophil-derived hCCL15/23 and mCCL6 can engage with CCR1 to facilitate eosinophilic airway inflammation." (PMID 40728992, 2025).
CCR1 also shares sentences with these, for which no sentence is quoted: acute myeloid leukemia (3 papers); colorectal tumor (3); allergies (2); bladder cancer (2); cardiac diseases (2); chronic lymphocytic leukemia (2); fibrosis (2); infarction (2); metabolic disorders (2); renal carcinoma (2); acute lung injury (1); acute pancreatitis (1); acute promyelocytic leukemia (1); acute respiratory distress syndrome (1); allergic asthma (1); alveolitis (1); anaphylaxis (1); aneurysm (1); autoimmune PAP (1); bacterial infections (1); bipolar disorder (1); bladder disease (1); brain ischemia (1); brain tumor (1); breast tumor (1); bronchiolitis (1); calcinosis cutis (1); cerebral infarction (1); chronic hepatitis C (1); chronic rhinosinusitis (1).
A further 61 diseases each share a sentence with CCR1 in 1 paper.